METTL1 (methyltransferase 1, tRNA methylguanosine)
Diseases named in the same sentence as METTL1 in open-access papers (continued):
Sharing a sentence is not in itself a finding about the gene and the disease.
cancer (continued). "The potential role of METTL1 in catalyzing m7G modifications is different in different cancers." (PMID 36071474, 2022). "Overexpressed METTL1 induced oncogenic cell transformation and cancer." (PMID 36118897, 2022). "However, deletion of NSUN2 and METTL1 in HeLa cells increased sensitivity to the anti-cancer drug 5-fluorouracil." (PMID 35721477, 2022). "However, there was an inconsistency between the activity and expression of METTL1 in other cancers (LUSC, COAD, LUAD as well as KICH)." (PMID 35432338, 2022). "In addition, the analyses of forty-five immune stimulators showed that METTL1 expression was positively related to TNFRSF18 as well as negatively associated with TNFSF15 and IL6R in nearly all cancers." (PMID 35432338, 2022). "Consistently, in patient-derived BCa tissues from our clinical center (n = 17), western blot assay and IHC staining revealed increased expression of METTL1 at the protein level compared with tissues adjacent to cancer, which was also confirmed in mRNA level by RT-qPCR assay." (PMID 36396627, 2022). "In addition, we also analyzed the significance of METTL1 on prognosis, and explored its mechanism through gene function enrichment analysis among pan-cancer." (PMID 35432338, 2022). "The evidence of METTL1-mediated cancer development is solid." (PMID 36092891, 2022). "Furthermore, subcutaneous xenograft model was constructed to study the effect of METTL1 knockdown on cancer cell growth in vivo." (PMID 34898034, 2021). "In addition, the compromised proliferation, migration and invasion observed in METTL1‐depleted T24 cells were rescued by overexpression of METTL1, confirming its role in promoting cancer progression." (PMID 34936728, 2021). "Moreover, the m7G tRNA methyltransferase METTL1 (Methyltransferase like 1) was reported to influence cancer cell viability." (PMID 33761868, 2021). "We hypothesized that METTL1 modulates many aspects of RNA metabolism, influences protein synthesis rate, and has numerous functional effects on cellular pathways and cancer progression." (PMID 34285249, 2021). "A subset of METTLs, such as METTL1, METTL7B, and NTMT1, which had higher frequency of gene alterations/overexpression in various cancers and/or were associated with poor disease prognosis, might function as cancer-promoters." (PMID 34285249, 2021). "Thus, we chose METTL1 as a candidate for further investigation of its expression correlation network and pathways in human cancer." (PMID 34285249, 2021). "Moreover, METTL1 is believed to be an important contributor to tumorigenesis as it regulates the sensitivity of cancer cells to the antitumor drugs cisplatin and 5-fluorouracil." (PMID 34838021, 2021). "Thus, METTL1 likely forms a functional network and regulates various RNA methylation events and pathways, promoting cancer progression." (PMID 34285249, 2021). "Besides METTL1 and NEIL2, several of the differentially methylated genes identified by analysis of associated promoter methylation, or of all genes, have roles in cancer biology." (PMID 33266012, 2020). "Overexpression of tRNA-modifying enzymes NSUN2 and METTL1 is widely observed among human cancers." (PMID 25233213, 2014). "Therefore, given its pronounced correlation with cancer stages and patient outcomes, the METTL1/WDR4 complex may serve as a promising molecular biomarker and potentially therapeutic stratification of HCC." (PMID 41208200, 2025). "Furthermore, a comprehensive analysis of pan-cancers also explored whether METTL1 could influence the efficacy of anti-PD-L1 therapy." (PMID 38385078, 2024). "It has been documented that SP1 could regulate METTL1 expression in cancer cells." (PMID 38977661, 2024). "Notably, METTL1’s molecular impact exhibits variability among different tumors, influencing key cancer hallmarks such as tumorigenesis, proliferation, stress response, the immune system and microenvironment cross-talk, and even regulation of the metastatic process." (PMID 38476632, 2024).
cancer (continued). "To test whether the stress-activated programme in Mettl1-/- cancer cells could alter their sensitivity to chemotherapy in vivo, we administered Docetaxel, commonly used for treating of metastatic castration-resistant prostate cancer (mCRPC), to mice-bearing tumours." (PMID 37660182, 2023). "This suggests a potential strategy for METTL1-overexpressing tumours, where the use of combination therapies, including METTL1 inhibitors, may synergise with chemotherapy or senolytic therapy to promote more effective elimination of tumour-initiating cells and persistent cancer cells." (PMID 37660182, 2023). "This study supplies forward-looking view on the significance of METTL1 in cancer immunotherapy and reveals the correlation between essential immunological indicators and METTL1, which might be advantageous to comprehend the potential mechanisms according to immune system and METTL1." (PMID 35432338, 2022). "Furthermore, depletion of METTL1 led to decreased m7G tRNA modifications and the overall global translation rate, suggesting that METTL1 may be able to be used as an anti-cancer target." (PMID 35721477, 2022). "In terms of the results that the high expression of METTL1 has various prognostic value in different cancers, we hypothesized that it could be an efficient strategy with clinical benefits to regulate METTL1 therapeutic activity according to different tumor types." (PMID 35432338, 2022). "Furthermore, in this study, we also revealed that two tRNA regulators, CTU2 and XPOT, may be functionally interconnected with METTL1 in cancer." (PMID 34285249, 2021). "Furthermore, functional annotation and pathway analysis of METTL1-associated proteins revealed that, in addition to the METTL1 cofactor WDR4, RNA regulators and DNA packaging complexes may be functionally interconnected with METTL1 in human cancer." (PMID 34285249, 2021). "Moreover, METTL1 was upregulated in high‐grade BC cancer tissues relative to low‐grade tumours, indicating that METTL1 may act as an oncogene in BC." (PMID 34936728, 2021). "Consistent with the view that inhibiting the methylase of tRNA may lead to chemotherapy resistance, silencing other tRNA methyltransferases, such as m7G methylase METTL1, will undergo methylation modification on several tRNA variable loops, which can enhance the sensitivity of cancer cells to 5-FU." (PMID 34778277, 2021). "Moreover, in other cancers, like glioblastoma and HCC, the high expression levels of METTL1 have been linked to a poorer prognosis, by unknown mechanisms." (PMID 33430133, 2021). "Thus, the combined activity of NSUN2 and METTL1 seems to be critical for 5-FU sensitivity of cancer cells, suggesting the presence of a conserved RTD-like pathway regulated by NSUN2 and METTL1 for participating in a surveillance system for tRNA quality control in human." (PMID 25233213, 2014). "Collectively, these findings indicate that METTL1 serves as a critical regulator of the PI3K/Akt and MAPK signaling pathways, contributing to the malignant phenotypes of various cancers." (PMID 40809384, 2025). "Recent findings have indicated that levels of the atypical methyltransferase METTL1 are elevated in cancer cells, thereby promoting glutamine synthase (GLUL) expression in an m6A-dependent manner, which in turn facilitates cancer cell proliferation." (PMID 40598593, 2025). "METTL1 and WDR4 promote cancer progression and poor prognosis by synergistically regulating the translation process." (PMID 41256854, 2025). "WB results showed that the levels of METTL1 (p < 0.0001), BRCA1 (p < 0.0001) and m7G (p < 0.0001) in cancer tissues were significantly higher than those in adjacent tissues (all p < 0.0001)." (PMID 41430564, 2025). "Screening these candidate miRNAs for expression correlation in HNSCC via the Pan-cancer subproject of the ENCORI database revealed significant negative correlations in 13 EIF1-miRNAs, 21 LARP1-miRNAs, and 1 METTL1-miRNA interactions." (PMID 40018039, 2025).
cancer (continued). "Conversely, in breast cancer, METTL1 mediates m7G modification to regulate cell cycle arrest and the translation of genes such as GADD45A and RB1, thereby inhibiting cancer cell proliferation." (PMID 41256854, 2025). "In osteosarcoma, METTL1 and WDR4 mediate m7G modification of tRNA, enhancing mRNA translation and promoting cancer cell proliferation, migration, and chemoresistance." (PMID 41256854, 2025). "An elevated protein expression of EIF4E, EIF4G3, LARP1, METTL1, NCBP1, NUDT4, and NUDT11 was discerned in the carcinoma samples, whereas the WDR4 expression was comparable between the tumor and adjacent non‐tumorous tissues." (PMID 40485623, 2025). "Therefore, the METTL1/WDR4 complex may be a potential target for cancer treatment." (PMID 39850560, 2024). "Previous studies have shown that METTL1 and WDR4 work together to add m7G modification in RNAs, and showed collaborative expression patterns in various cancers, including AML." (PMID 38268051, 2024). "Recent studies have highlighted the role of the METTL1/WDR4 complex in elevated mRNA translation and enhanced tRNA stability, which contributes to the development of several cancers." (PMID 38721006, 2024). "For instance, deregulations of tRNA modification enzyme genes METTL1 and ALKBH1 induced impaired translation and aberrant cancer progression in vitro and in vivo." (PMID 39695074, 2024). "METTL1 is regulated by protein kinase B (AKT) and ribosomal S6 kinase and plays a notable role in the self‐renewal of embryonic stem cells and cancer cells." (PMID 38721006, 2024). "The METTL1‐WDR4 complex, critical for tRNA stability and cancer development, relies on WDR4 to scaffold METTL1 and tRNA interaction." (PMID 39377984, 2024). "The silencing of METTL1 and WDR4 inhibits the proliferation, migration and invasion of cancer cells, while the forced expression of METTL1 contributes to tumor progression." (PMID 39850560, 2024). "Recent studies have found that METTL1/WDR4 mediated RNA m7G modification plays important biological roles in human malignancies, such as cancers in the liver, colorectal, esophageal, bladder, and lung." (PMID 38268051, 2024). "In bladder cancer, METTL1-m7G-mediated tRNA methylation promotes EGFR/EFEMP1 translation and thus promotes angiogenesis and cancer cell metastasis." (PMID 39019857, 2024). "In a comprehensive analysis of pan-cancers, overexpression of METTL1 and WDR4 was correlated with more Tregs infiltration in diverse types of cancers." (PMID 38385078, 2024). "The expression levels of METTL1 and WDR4 are significantly increased in human cancers and correlated with poor prognosis." (PMID 38001714, 2023). "This illustrates the significant role that METTL1 and WDR4 play in mediating cancer drug resistance and is expected to be a future therapeutic target." (PMID 37710294, 2023). "However, it is still unclear whether METTL1 is involved in the survival of cancer cells." (PMID 37660182, 2023). "The expression levels of METTL1 and WDR4 significantly correlated with the sensitivity of cancer cells to antitumor drugs." (PMID 36635678, 2023). "METTL1-mediated m7G modification on Arg-TCT-4–1 tRNA induced oncogenic cell transformation and cancer via increasing mRNA translation of growth-promoting proteins." (PMID 37612540, 2023). "In our study, we found that the expression levels of METTL1 and WDR4 were correlated with immunoinhibitors in pan-cancer datasets." (PMID 36226166, 2022). "We also assessed the changes in the expression of m7G related regulatory genes in NSCLC with regards to the genetic and transcriptional aspects and evaluated the correlation of METTL1 and WDR4 expression with TMB, MSI and immunotherapy in pan-cancer." (PMID 36226166, 2022). "We found 5 primary regulator genes (EIF4E1B, METTL1, NUDT11, NUDT10 and NUDT4B) were differential expressed in more than 15 cancer types." (PMID 36092891, 2022).
cancer (continued). "The results showed m7G methyltransferases, such as METTL1 and WDR4, were upregulated in a wide range of cancers, while RNA-binding and decapping enzymes (NUDT4, NUDT16, and NUDT10) were significantly downregulated." (PMID 35592316, 2022). "Two kinds of m7G tRNA modifying enzymes, METTL1 and NSUN2, determine 5-Fluorouracil (a drug used in the treatment of cancer) sensitivity in human cancer cells." (PMID 36118897, 2022). "To investigate the relationship between METTL1/WDR4 expression and immunotherapy response in pan-cancer, we first explored the correlation between the expression of METTL1 and WDR4 with the expression of immunoinhibitors in the TISIDB database." (PMID 36226166, 2022). "We found that 30 cancers, except for ACC, CHOL, and UCS, revealed correlation between the stemness indices and METTL1 expression." (PMID 35432338, 2022). "We identified a subset of METTL genes, notably METTL1, METTL7B, and NTMT1, with high frequencies of genomic amplification and/or up-regulation at both the mRNA and protein levels in a spectrum of human cancers." (PMID 34285249, 2021). "Similarly, in intrahepatic cholangiocarcinoma, METTL1 and WDR4 mediate m7G tRNA modification to enhance mRNA translation, promoting cancer progression and contributing to poor prognosis." (PMID 41256854, 2025). "The concept of combining METTL1 inhibitors with ICIs may hold promise in specific contexts (e.g., ICC or HCC), but its efficacy is likely to depend on the cancer type, tumor microenvironment, and immune landscape." (PMID 41562049, 2025). "The collaborative expression between METTL1 and WDR4 was identified among various cancers." (PMID 38268051, 2024). "METTL1 may be effective in the treatment of HNSC and other cancers through the targeting of other immune checkpoints, including the T-cell Ig and ITIM structural domains (TIGIT), or the cytotoxic T lymphocyte-associated protein 4 (CTLA-4)." (PMID 39289775, 2024). "GSEA analysis showed that genes of proliferation- and metastasis-related pathways were more likely to be enriched in high METTL1 expression cohorts in KIRC, LGG, and LIHC, demonstrating that METTL1 is a poor patient prognosis biomarker in these cancers and can be used to assess patient survival." (PMID 39289775, 2024). "Furthermore, numerous recent studies have explored the relationship between m7G modification, METTL1/WDR4 complexes, and various diseases, particularly cancer." (PMID 38822363, 2024). "Dysregulation of tRNA m7G modification by METTL1/WDR4 complex and consequent codon-biased translation may contribute to various types of cancers 44,45." (PMID 38385078, 2024). "In addition, METTL1 or WDR4 knockouts lead to impaired cell cycle gene function, affect tRNA function, ribosome suspension and mRNA translation, and inhibit cancer development." (PMID 39850560, 2024). "Meanwhile, in cancer cells, METTL1/WDR4 mainly promotes the translation of genes related to cell proliferation, drug resistance, and angiogenesis by mediating m7G methylation of tRNA, so that cancer cells can better survive in the environment." (PMID 39019857, 2024). "The m7G regulatory factors methyltransferase 1 (METTL1) and WD Repeat Domain 4 (WDR4) participate in the regulation of various cancer types, including HNSCC, liver cancer, bladder cancer, and lung cancer, by changing the m7G modification levels of miRNAs and tRNAs 18,19." (PMID 39440068, 2024). "Overexpression of m7G writers METTL1/WDR4 results in an increased abundance of m7G‐methylated tRNA, which in turn upregulates the translational efficiency of cell cycle‐regulating transcripts to drive cancer progression." (PMID 39041608, 2024). "Thus, a common link between METTL1 and PI3K and MAPK pathways is described across several cancers, implying the cross-talk between key signaling pathways and post-transcriptional events resulting in higher proliferation and tumorigenesis." (PMID 38476632, 2024).
cancer (continued). "For multiple immunosuppressive agents, KDR and CD274 showed the most significant negative correlation with METTL1 in almost all cancers." (PMID 39289775, 2024). "In addition, METTL1/WDR4 regulates miRNA maturation in an m7G‐dependent manner, further contributing to cancer progression in lung and bladder cancer." (PMID 39041608, 2024). "While there are currently no METTL1-specific inhibitors available, recent breakthroughs in the field of epitranscriptomics and cancer have led to the successful development of inhibitors targeting METTL3, an RNA 6-methyladenosine transferase." (PMID 37660182, 2023). "For diverse immune inhibitors, KDR and CD274 demonstrated the most significant negative relationship with METTL1 among nearly all cancers." (PMID 35432338, 2022). "METTL1 and NSUN2, determine 5-Fluorouracil sensitivity in human cancer cells." (PMID 36118897, 2022). "METTL1 was not intimately related to gender, age, tumor stage, or treatment outcome of the various cancers, but it displayed potential prognostic significance for evaluating patient survival." (PMID 35432338, 2022). "However, it should be noted that future studies are needed to address the pathophysiological significance and molecular mechanisms of the identified METTLs, such as METTL1, NTMT1, and METTL26, in promoting cancer development and progression." (PMID 34285249, 2021). "During the occurrence and development of tumors, the METTL1/WDR4 complex modifies the tRNA subpopulation that decodes m7G-dependent codons, promotes stable ribosome extension, and increases the cell cycle and translation efficiency of oncogenic mRNA, thereby promoting cancer progression." (PMID 41501031, 2026). "Notably, METTL1 and WDR4 are downregulated in cancers that originate from the endocrine system." (PMID 39041608, 2024). "In the beginning, we investigated the relationship between METTL1 and clinical information and found there were no obvious differences of METTL1 expression among gender, age, tumor stage, status as well as treatment outcome in most cancer types." (PMID 35432338, 2022). "Although the effect of METTL1 on tRNA may be cancer-promoting, there is no direct evidence that m7G modification plays a role in cancer cells." (PMID 35614935, 2022). "What’s more, the expression of some writer genes (METTL1 and WDR4) and reader genes (AGO2 and NCBP2) was significantly upregulated in most cancers, while the expression of some eraser genes (NUDT12 and NUDT16) and some reader genes (EIF4E3) were downregulated in most cancers." (PMID 36339001, 2022). "Pathway analysis revealed that the altered miRNAs were involved in some key signaling pathways of cancer such as “MAPK signaling pathway”, “Wnt signaling pathway”, “AMPK signaling pathway”, and “Ras signaling pathway”, suggesting METTL1 could regulate tumorigenesis in a miRNA-dependent manner." (PMID 36396627, 2022). "We found that several METTLs, including METTL1, had a significantly positive correlation between DNA copy number, mRNA, and protein levels (Spearman rho > 0.5, FDR < 0.001), suggesting that increasing DNA copy number contributed to increased METTL1 mRNA and protein levels in a subset of cancers." (PMID 34285249, 2021). "We identified a subset of METTL genes, notably METTL1, METTL2A, METTL2B, METTL7B, NTMT1, and METTL26, with high frequencies of genomic amplification and/or up-regulation, while METTL7A and METTL24 were under-expressed, at both mRNA and/or protein levels in a spectrum of human cancers." (PMID 34285249, 2021). "Indeed, although the molecular effectors vary across cancer types, and some mechanisms are not yet totally uncovered, METTL1-dependent m7G tRNA modification is essential for modulating cancer cell responses to stress and therapeutic challenges, being crucial for resistance acquisition." (PMID 38476632, 2024).